S100A4 (S100 calcium binding protein A4)
Diseases named in the same sentence as S100A4 in open-access papers (continued):
Sharing a sentence is not in itself a finding about the gene and the disease.
silicosis (1 paper, 2022). Silicosis is a respiratory disease caused by breathing in (inhaling) silica dust. "Second, we only observed the association between S100A4 and silicosis, but detail molecular mechanisms are still unknown." (PMID 35379204, 2022). "Serum S100A4 were significantly increased in silicosis patients (70.84 (46.22, 102.46) ng/ml) compared with control subjects (49.84 (42.86, 60.02) ng/ml)." (PMID 35379204, 2022). "In receiver operating characteristic (ROC) analyses, S100A4 > 61.7 ng/ml had 63.4% sensitivity and 83.3% specificity for silicosis, and the area under the curve (AUC) was 0.707." (PMID 35379204, 2022). "The role of S100A4 as a potential therapeutic target for silicosis needs to be evaluated in further studies." (PMID 35379204, 2022). "Similar to these studies, we found that the levels of S100A4 were increased in the serum of patients with silicosis and in the lung tissues of silicotic mice." (PMID 35379204, 2022). "Compared with CG, the levels of S100A4 were significantly increased in silicosis patients (70.84 (46.22, 102.46) ng/ml vs (49.84 (42.86, 60.02) ng/ml)." (PMID 35379204, 2022). "Collectively, we found that S100A4 levels were increased in the serum of silicosis patients and the alveolar macrophages and lung tissues of silicosis mice." (PMID 35379204, 2022). "ROC curve analysis was used to identify the discriminatory power of S100A4 in serum for silicosis." (PMID 35379204, 2022). "Furthermore, the alveolar macrophages in mice with silicosis exhibited higher expression of S100A4 compared with the control mice." (PMID 35379204, 2022). "We found that 61.7 ng/ml was the cut-off value of serum S100A4 for detecting silicosis." (PMID 35379204, 2022). "The secretion of S100A4 was correlated with inflammation, fibrosis and lung function in silicosis." (PMID 35379204, 2022). "And further mechanism of S100A4 in silicosis should be investigated in vivo and in vitro." (PMID 35379204, 2022). "Hence, future studies should enlarge the sample size to explore the clinical significance of S100A4 in early diagnosis of silicosis." (PMID 35379204, 2022). "This study aims to investigate the possible role of S100A4 in silicosis." (PMID 35379204, 2022). "However, the detailed mechanism of S100A4 in silicosis needs further investigation." (PMID 35379204, 2022). "Then, our study also found that S100A4 was mainly expressed at the cellular nodules of silicotic mice, and primary AMs of silicotic mice exhibited a higher S100A4 level compared to control mice, suggested that AMs may be an important source of S100A4 in silicosis." (PMID 35379204, 2022). "According to these findings, we speculate that elevated S100A4 may mainly origin from alveolar macrophages after engulfing silica in the inflammatory stage and contribute to fibrosis in silicosis by promoting the transition of fibroblasts and alveolar epithelial cells to myofibroblasts." (PMID 35379204, 2022). "To investigate the possible role of S100A4 in silicosis, we first detected the secretion of S100A4, inflammatory indicator IL-6 and TNF-α, and fibrotic cytokine TGF-β1 and CTGF in the serum of patients with silicosis." (PMID 35379204, 2022). "However, the relationship between S100A4 and silicosis is still unknown." (PMID 35379204, 2022). "S100A4 expression in lung tissues and primary alveolar macrophages (AMs) of mice with and without silicosis was detected by immunohistochemistry (IHC)/real-time PCR." (PMID 35379204, 2022). "This hypothesis can be supported by the findings in our study that serum S100A4 levels were positively correlated with TGF-β1 and IL-6, suggested a possible role of S100A4 in inflammation and fibrosis of silicosis." (PMID 35379204, 2022). "In this study, serum levels of S100A4, transforming growth factor-β1 (TGF-β1), connective tissue growth factor (CTGF), interleukin-6 (IL-6) and tumour necrosis factor-α (TNF-α) in patients with silicosis (n = 42) and control group (CG, n = 12) were measured by ELISA." (PMID 35379204, 2022).
ulcerative colitis (1 paper, 2012). An inflammatory bowel disease involving the mucosal surface of the large intestine and rectum. "On the other hand, S100A8, S100A9, S100A10, and S100A4 displayed heterogeneous expression patterns in ulcerative colitis patients showing neoplasia." (PMID 23166536, 2012).
uterine cancer (1 paper, 2021). Primary or metastatic malignant neoplasm involving the uterine corpus and/or the cervix. "In this respect, EMT and S100A4 has been linked to breast, lung, gastric, and uterine cancer." (PMID 33805347, 2021).
uterine carcinosarcoma (1 paper, 2022). A usually aggressive malignant neoplasm arising from the uterine corpus and less often the cervix. "For instance, S100A4/non-muscle myosin II signaling has been associated with epithelial–mesenchymal transition and stemness in uterine carcinosarcoma, while the inhibition of S100A8 expression is reported to promote apoptosis through the suppression of AKT phosphorylation." (PMID 35042454, 2022).
vasculitis (1 paper, 2026). "Original human studies investigating S100A8/9, S100A12, S100A4, and S100A10 in any form of vasculitis or related vascular inflammation were included." (PMID 41958648, 2026).
vitamin D deficiency (1 paper, 2016). A nutritional condition produced by a deficiency of VITAMIN D in the diet, insufficient production of vitamin D in the skin, inadequate absorption of vitamin D from the diet, or abnormal conversion of vitamin D to its bioactive metabolites. "Vitamin D deficiency alone did not influence the number of fibroblasts (FSP1/S100A4 + cells/0.087 mm2) in the renal cortex and renal medulla." (PMID 27369932, 2016).
vitiligo (1 paper, 2023). Generalized well circumscribed patches of leukoderma that are generally distributed over symmetric body locations and is due to autoimmune destruction of melanocytes. "We isolated fibroblasts from both control and vitiligo mouse tails, both showing typical morphology and expressing classic fibroblast marker S100A4." (PMID 36672151, 2023).
tumor (453 papers, 1999 to 2026). "FGFR1 inhibition not only enhances radiosensitivity but also downregulates key effectors such as S100A4, which are associated with tumor stemness, mesenchymal transition, and microenvironmental modulation." (PMID 41002392, 2025). "A total of 34 cell subsets were identified, with the Vtnfl/fl S100a4‐Cre+ group showing a reduced proportion of tumor‐associated macrophages (TAMs) compared to the control group." (PMID 40538300, 2025). "In cancer, S100a4 -/- mice are partially protected from tumor growth due to loss of circulating MDSCs." (PMID 40078995, 2025). "S100A4 simultaneously promotes the differentiation of tumor-associated macrophages (TAMs) by enriching various cytokines, thereby shaping a TME that supports the survival of cancer cells." (PMID 40093000, 2025). "RAGE signaling activated by S100A4 has been implicated in various inflammatory and oncogenic processes, including tumor growth, metastasis, and resistance to apoptosis." (PMID 41155277, 2025). "Genetically, CRISPR screening identified that the loss of genes such as MT1E and S100A4 promotes tumor cell migration." (PMID 41142598, 2025). "Elevated S100A4 expression is associated with enhanced tumor motility, invasion, and poor prognosis across multiple cancer types, including BC." (PMID 41404073, 2025). "S100A4-expressing macrophages can also be recruited to the liver to induce fibrosis as an adverse outcome in anti-tumor immunotherapy associated toxicity." (PMID 40078995, 2025). "Cluster 1 expressed S100a4, S100a6, and Spp1, genes associated with tumor progression and metastasis." (PMID 41567211, 2025). "In HCC, depleting S100A4 in stromal cells reduces tumor stemness properties and inflammation-associated pathological features." (PMID 40078995, 2025). "High S100A4 expression is linked with tumor aggressiveness, whereas low S100A14 expression is associated with advanced disease stages and increased metastasis." (PMID 39205741, 2024). "Consistently, X‐ray imaging confirmed reductions in bone density by bone loss as the tumour increased, but reducing S100A4 unequivocally protected against net bone loss by alleviating the metastatic capacity of RelB." (PMID 39415352, 2024). "S100A4, a calcium-binding protein associated with cell migration, invasion, and tumor metastasis, indicates high invasive and metastatic potential when expressed." (PMID 39591300, 2024). "S100A4 is a member of the damage-associated molecular pattern family, and is overexpressed in many tumors and involved in tumor metastasis." (PMID 38584705, 2024). "To provide further support for the proliferative effect of tumor organoid factors on SMCs, we also assessed the expression of S100A4, a Ca2+-binding protein associated with SMC proliferation." (PMID 38339292, 2024). "In the present study, we performed the complex analysis of mRNA and protein expression of crucial regulators of tumor angiogenesis and tumor progression, expressed by tumor-associated macrophages (TAMs): S100A4, SPP1 and SPARC." (PMID 36895491, 2023). "In cluster 4, which mostly existed in the gem group, cells expressed high levels of CCR2, CCL2, and S100A4 genes that are associated with tumor progression and metastasis." (PMID 37324492, 2023). "Although S100A4 can be associated with both malignant and non- malignant diseases, in cancer, S100A4 demonstrates enhanced cell growth and motility, tumor progression, and metastasis formation." (PMID 36674695, 2023). "Specifically, NEAT1+ tumor cells with the CSCs phenotype were observed in the initial portion, followed by two separate trajectory branches: apoptotic CSCs FSTL1+ tumor cells and EMT tendency and immune-associated S100A4+ tumor cells." (PMID 37430270, 2023). "The combined MACC1/S100A4 biomarker robustly identified CRC patients at high risk for poor MFS by tumor RNA analysis and predicted poor OS from liquid biopsy analyses." (PMID 36008464, 2022).
tumor (continued). "Upregulation of S100a4 in TGFBR1-CA ovaries is likely associated with tumor formation, as S100a4 is implicated in multiple cellular and inflammatory events that promote tumorigenesis." (PMID 35565312, 2022). "Together, previous studies indicate that S100A4 function is highly context-dependent, and in cancer, it is associated with tumor aggressiveness." (PMID 35140215, 2022). "It would be of great advantage to set up a systematic analysis of AGE/S cell lines from different tumor stages, origins and mutational backgrounds in order to understand the role of S100A4 in the context of other mediators of metastasis." (PMID 35326507, 2022). "A reduction of lipid content was also observed in S100A4-deficient TAMs derived from E0771 tumor grafts." (PMID 34145030, 2021). "The S100A4 gene was originally isolated and characterized from metastatic cells and then associated to tumor metastasis." (PMID 33946884, 2021). "It was identified to be closely associated with tumor metastasis, transfection of S100A4 can enhance the tumorigenic potential and stimulate the metastasis in vivo." (PMID 33691630, 2021). "Abnormal S100A4 expression is positively associated with lung cancer tumour progression and importantly its function demonstrably contributes to BC metastases migration to the lungs." (PMID 33807045, 2021). "The presence of cells expressing αSMA, Vimentin, and S100A4 in the IMPC stroma suggested a role for tumor-associated fibroblasts in the IMPC microenvironment." (PMID 33761962, 2021). "S100A4 has been reported to be associated with cancer cell migration and metastasis and is important in tumor onset and progression." (PMID 35069135, 2021). "The importance of the RANTES‐S100A4 axis has been further verified by planting RANTES‐overproducing tumour cells in wild‐type and S100A4 gene‐deficient mice." (PMID 32307910, 2020). "The combined outcomes in the present meta-analysis also demonstrated that a significant association was observed between S100A4 expression and tumor differentiation in NSCLC." (PMID 32696952, 2020). "As a metastasin, S100A4 is associated with numerous cytoskeletal proteins, such as actin, myosin, and tropomyosin, increasing the tumor progression and metastasis." (PMID 32154176, 2020). "No publication bias was observed for the association between S100A4 expression and OS, gender, age, tumor size, LNM, TNM stage, smoking, or pathological subtype." (PMID 32696952, 2020). "Another cytokine, regulated on activation in normal T Cell expressed and secreted (RANTES) can stimulate the secretion of extracellular S100A4, which is associated with microvesicles (MVs) that shed from plasma membranes of tumours and normal cells." (PMID 32307910, 2020). "Previous studies have reported overexpression and association of S100A4 with tumor aggressiveness, metastasis, and poor survival in patients in multiple cancers." (PMID 31881983, 2019). "S100 belongs to one of the largest subfamilies of EF-hand calcium binding proteins, and S100A4 overexpression is strongly associated with tumor aggressiveness." (PMID 31101063, 2019). "In, TNBCs, expression of a nuclear/cytoplasmic S100A4 is associated with high histological tumor grade and inferior metastasis-free and overall survival." (PMID 31844158, 2019). "In wild type and S100A4-deficient mouse models, tumor cell-derived CCL5 on S100A4 release into blood circulation ultimately increases the metastatic burden in mice." (PMID 30925930, 2019). "The chi-square analysis showed that the positive expression of S100A4 was associated with tumor size (P = 0.028), differentiation (P = 0.007), TNM stage (P = 0.000), and lymph node metastasis (P = 0.025)." (PMID 31526392, 2019). "Increased expression of S100A4 is associated with aggressiveness of a tumor, metastasis, and poor patient survival." (PMID 31881983, 2019). "A statistically significant association between the status of S100A4 staining in the tumor tissue and the age groups was observed (p <0.05)." (PMID 30111999, 2018).
tumor (continued). "It was found that the S100A4 staining distribution was statistically associated with the age, localization of the tumor, TNM stages, and survival." (PMID 30111999, 2018). "A statistically significant association between the tumor stages and S100A4 staging was present (p <0.05)." (PMID 30111999, 2018). "The distribution of the S100A4 protein staining in the tumor tissue was associated with the age groups, tumor localization, TNM staging, and patient survival with statistical significance." (PMID 30111999, 2018). "We decided to study the link between S100A4 and MDSCs based on the fact that high levels of exogenous S100A4 are a hallmark of tumor tissues." (PMID 29556233, 2018). "Our findings demonstrate that S100A4 promotes lung tumor development through inhibiting autophagy in a β-catenin signaling and S100A4 receptor RAGE-dependent manner, which provides a novel mechanism of S100A4-associated promotion of tumor development." (PMID 29449540, 2018). "In particular, it is reported that S100A1 and S100A7 are linked to tumor growth, while S100A4 and S100A8 are linked to metastasis." (PMID 28615627, 2017). "Several recent publications have demonstrated an association between S100A4 and non-tumor pathophysiologies, such as tissue fibrosis, inflammation, immune reaction, neuroprotection, and cardiovascular events." (PMID 29204268, 2017). "S100A4-promoted cancer metastasis associates with numerous tumor-related proteins, such as actin, myosin, and tropomyosin." (PMID 29069865, 2017). "In humans, upregulation of S100A4, both in tumor and stroma cells, was associated with poor prognosis and low survival of patients with cancer." (PMID 29204268, 2017). "The underlying molecular mechanisms responsible for S100A4 activities in tumor metastasis and the induction of S100A4 upregulation in cancers; 3)." (PMID 29069865, 2017). "S100A4 was identified by Ebradlize and colleagues, and shown to be associated with tumor metastasis for the first time." (PMID 29069865, 2017). "Taken together, it is well established that S100A4 has profound impact in many types of solid cancers, where its upregulation causes tumor progression and metastasis formation." (PMID 27331819, 2016). "Pooled data also suggested a trend towards positive expression of S100A4 which was associated with low degree of tumor differentiation and status of distant metastasis, though statistically significantly it was not reached." (PMID 26903691, 2016). "Both niclosamide-treated mouse groups showed enhanced overall survival compared with the solvent-treated mice linked to long-term inhibition of tumor growth and liver metastasis formation, and to reduction of S100A4 expression." (PMID 27331819, 2016). "S100A4, a multifunctional protein localized in the nucleus, cytoplasm, and extracellular space, is strongly associated with metastatic tumour progression." (PMID 26880885, 2016). "Through these extensive biological functions, S100A4 expression is associated with tumor progression and is identified as a prognostic indicator in many human malignancies." (PMID 27127879, 2016). "Recent studies have demonstrated that S100A4 protein is closely associated with tumor growth, progression and patient outcome." (PMID 25339497, 2015). "By using transgenic and knockout mouse models stroma-cell derived S100A4 was shown to have a causal role in tumor progression." (PMID 25884510, 2015). "Animals injected with S100A4-deficient S2VP10 cells showed a significant delay in tumor development, and these S100A4-deficient tumors had remarkably reduced FAK and Src activation (when compared to control tumors)." (PMID 25677816, 2015). "The in vivo and in vitro data are consistent and support the effects of loss of S100A4 in inhibition of tumor progression." (PMID 25677816, 2015). "In pulmonary metastasis, S100A4 deficiency was shown to determine low vascularity, which in turn suppresses development of secondary tumours." (PMID 25598217, 2015).